INS (insulin)
Diseases named in the same sentence as INS in open-access papers (continued):
Sharing a sentence is not in itself a finding about the gene and the disease.
Insulin resistance (continued). "And excess fatty acids not only induce hepatic insulin resistance but also impair insulin clearance which is proportional to the amount of liver fat in NAFLD." (PMID 40672429, 2025). "The dietary supplementation of ginger has also been shown to improve fasting glucose, HbA1C, insulin, and the homeostatic model of insulin resistance, HOMAIR." (PMID 40732990, 2025). "Most studies define MHO as having either 0, 1 or 2 components of metabolic syndrome, while many others define MHO as insulin‐sensitive based on the homeostasis model assessment of insulin resistance." (PMID 39679900, 2025). "Abnormal fat accumulation not only releases various inflammatory factors (e.g., tumor necrosis factor-α and interleukin-6) but also disrupts insulin signaling, further worsening insulin resistance." (PMID 39920728, 2025). "CNIs contribute to the development of NODAT by reducing insulin secretion, increasing insulin resistance, and having a toxic effect on pancreatic beta-cells." (PMID 39941214, 2025). "The factors inhibit insulin action, exacerbating insulin resistance, disrupting glucose regulation, and significantly raising the risk of prediabetes." (PMID 41211213, 2025). "Insulin resistance (IR), a metabolic disorder characterized by reduced responsiveness to insulin, has been increasingly recognized as a key factor in the pathogenesis of CRC." (PMID 41479778, 2025). "Insulin’s immunomodulating action is also compromised in conditions of insulin resistance: this compromises its capacity to reduce pro-inflammatory molecules in macrophages such MCP-1, so encouraging inflammation and atherogenesis." (PMID 41007785, 2025). "In fact, a phenomenon known as “selective insulin resistance” occurs, where insulin signaling selectively activates certain metabolic pathways, such as de novo lipogenesis, without affecting others." (PMID 40138287, 2025). "A key feature of metabolic aging is insulin resistance, a condition where cells fail to respond adequately to insulin signaling, leading to hyperglycemia and compensatory hyperinsulinemia." (PMID 40649702, 2025). "As an activator of SIRT1, resveratrol induces PGC- 1α’s activity to improve insulin sensitivity in high-fat diet obese mice and protects them from the development of obesity and insulin resistance." (PMID 40438494, 2025). "Our results revealed that STZ injection disrupted pancreatic beta cell function, resulting in elevated levels of FBG and HbA1c, increased blood insulin levels, and insulin resistance, indicating successful establishment of the T2DM model." (PMID 40540468, 2025). "Increased TGs and FFAs cause not only oxidative stress and systemic inflammation, but also insulin resistance and β-cell dysfunction by inhibiting insulin signaling." (PMID 41190158, 2025). "Insulin resistance in skeletal muscle is a key factor in the impairment of insulin function, and reduced glucose uptake capacity in skeletal muscle significantly contributes to the development and progression of type 2 diabetes." (PMID 41154025, 2025). "Insulin resistance (IR) is a state in which the body is insensitive to the action of insulin, resulting in a decrease in insulin’s efficacy in promoting glucose uptake and utilization." (PMID 39959622, 2025). "Type 2 diabetes (T2D) is a complex metabolic disease characterized by chronic hyperglycemia due to insulin resistance and inadequate insulin secretion." (PMID 40871736, 2025). "Increased ectopic deposition also adds problems in peripheral insulin signaling and complications related to systemic insulin resistance and the development of type 2 diabetes." (PMID 40076851, 2025). "Within 12 months after diagnosis, insulin resistance correlated positively with insulin antibody titers even after adjustments for sex, age, BMI, daily insulin dose, and β-cell residual secretory capacity." (PMID 39998445, 2025).
Insulin resistance (continued). "In the last two decades, mounting evidence has emerged indicating that hyperinsulinemia can in turn aggravate insulin resistance, resulting in higher insulin secretion, at least until beta-cell failure occurs." (PMID 40568093, 2025). "When insulin resistance is due to corticosteroid treatment in KRs, a combination of rapid-acting insulin with slow-acting insulin is recommended." (PMID 40142909, 2025). "Our study also suggests that the fasting insulin levels and insulin resistance index are higher in the adolescent development group compared to the adolescent-undeveloped group." (PMID 40150457, 2025). "In tissues that are sensitive to insulin, such as skeletal muscle and adipose tissue, oxidative stress can disrupt insulin receptor signaling, resulting in insulin resistance." (PMID 40862129, 2025). "This central insulin resistance impairs the anorexia and metabolic effects of insulin in the brain, creating a self-reinforcing vicious cycle leading to systemic metabolic dysfunction." (PMID 41515216, 2025). "These include hyperlipidemia, insulin resistance, and new-onset diabetes mellitus, believed to result from impaired pancreatic β-cell function, mitochondrial dysfunction, and suppression of insulin gene transcription." (PMID 40572755, 2025). "Given the brain’s high sensitivity to insulin, peripheral insulin resistance results in reduced insulin signaling in the central nervous system (CNS), subsequently leading to alterations in brain metabolism." (PMID 39966707, 2025). "In patients with T2DM, impaired insulin signaling leads to the development of insulin resistance and abnormal glycemic control." (PMID 40747301, 2025). "When a patient has hyperinsulinemia or T2DM, it is found that PP is secreted more abundantly from the pancreas due to the increased amount of insulin because of insulin resistance and high levels of blood glucose." (PMID 39857716, 2025). "Specifically, iron accumulation enhances the expression of resistin and retinol-binding protein 4 (RBP-4), while it inhibits the expression of insulin sensitizing leptin, resulting in insulin resistance." (PMID 39941760, 2025). "TNF, and interleukin-6 (IL-6) have been shown to disrupt insulin signaling, reducing glucose uptake and contributing to insulin resistance." (PMID 40453076, 2025). "Specifically, 47 targets were observed in GO analysis, observation shows INSR, NF-κB, Akt, GSK-3 and Raf, which regulates insulin signalling and insulin resistance pathway, these pathways contribute in the development of specifically type 2 diabetes." (PMID 40126146, 2025). "Pancreastatin has been shown to impair glucose-stimulated insulin secretion and induce insulin resistance, whereas catestatin appears to exert anti-obesity effects by enhancing lipid mobilization and leptin signaling." (PMID 41480370, 2025). "A review by AW reported that an altered gut microbiota can lead to decreased SCFA production and increased inflammation and can affect insulin secretion and pancreatic β-cell sensitivity, leading to insulin resistance." (PMID 39997751, 2025). "A prior in vitro study demonstrated that UPPs enhanced glucose uptake in normal 3T3-L1 adipocytes and reinstated insulin-stimulated glucose uptake in adipocytes with obesity-induced insulin resistance." (PMID 40278284, 2025). "Insulin resistance, the diminished cellular response to insulin, is a defining feature of metabolic disorders such as T2DM." (PMID 40564201, 2025). "Therapies also target other pathways that improve insulin signaling, such as inhibiting oxidative stress, a known culprit in developing insulin resistance." (PMID 39873298, 2025). "This reduction subsequently leads to increased insulin levels, disturbances in glucose metabolism, and insulin resistance." (PMID 40970032, 2025).
Insulin resistance (continued). "Our objective is to conduct a comprehensive comparison of the metabolic profiles of individuals with insulin resistance and their insulin-sensitive counterparts using the TyG index as a reliable marker to classify insulin resistance status." (PMID 40422918, 2025). "Insulin resistance is a pathological condition characterized by a reduced sensitivity of target tissues to insulin and impaired glucose uptake and metabolism, contributing to metabolic dysregulation." (PMID 40475963, 2025). "Significant reductions in fasting blood glucose, insulin concentrations, and insulin resistance, alongside improvements in sensitivity indices such as HOMA-IR and QUICKI, have been documented in meta-analyses." (PMID 40725859, 2025). "Hyperinsulinemia or IR was defined as fasting insulin or homeostasis model assessment of insulin resistance [HOMA-IR] above the 75th percentile in all participants who underwent blood tests on fasting insulin, glucose, and hemoglobin A1c." (PMID 40365140, 2025). "Research has demonstrated that these compounds possess multiple antidiabetic mechanisms: they can inhibit key enzymes involved in glucose metabolism, prevent the development of insulin resistance, and normalize blood glucose and insulin levels." (PMID 40864768, 2025). "This is attributed to compromised effects of native GIP on adipose tissue resulting in clearance of triglyceride from adipose and liver stores, thereby substantially improving insulin sensitivity and alleviating insulin resistance." (PMID 40024571, 2025). "Insulin resistance, a condition in which the body’s cells become less responsive to insulin, is a key factor contributing to various metabolic disorders, including type 2 diabetes and sarcopenia (muscle wasting)." (PMID 40626218, 2025). "Since glucocorticoids can induce insulin resistance, dexamethasone and hydrocortisone were removed from the growth media 48 hours before insulin stimulation." (PMID 40231468, 2025). "Among the 23 lipids that were inversely associated with physical activity levels, 16 consistently showed positive associations with both fasting glucose and insulin resistance (HOMA-IR), as well as inverse associations with insulin sensitivity (QUICKI)." (PMID 41286497, 2025). "An additional mechanism involves the enhanced delivery of FFAs into the portal system, which directly impacts hepatic insulin handling and promotes insulin resistance." (PMID 41284359, 2025). "Alterations in the plasma insulin levels and insulin resistance directly contribute to altered lipid metabolism via de novo lipogenesis, inhibition of lipolysis, and ectopic fat deposition." (PMID 40896083, 2025). "Specifically, the study will assess changes in fasting plasma glucose and insulin levels as surrogate markers for insulin resistance." (PMID 41157306, 2025). "Insulin resistance is a major risk factor for developing T2DM, hallmarked by the impaired response of the body to insulin, resulting in elevated blood sugar levels." (PMID 40564223, 2025). "GDM is promoted by insulin resistance, release of insulin-antagonistic hormones and systemic inflammatory response during pregnancy." (PMID 39963668, 2025). "Variants in the SLC30A8 gene can impair insulin secretion and action, key features in T2DM and insulin resistance, which are precursors to obesity." (PMID 41009965, 2025). "The activation of signalling pathways, such as NF-kB and JNK, has been reported to be regulated by obesity within the adipose tissue, and the released inflammatory factors affect the insulin signalling pathway, thereby leading to worsened insulin resistance." (PMID 41226484, 2025). "Several lines of evidence suggest that insulin resistance disrupts insulin‐signaling pathways in the brain, leading to impairment in glucose uptake and utilization by neurons." (PMID 39992249, 2025). "For instance, TNF-α, IL-6, and leptin can induce insulin resistance, while adiponectin enhances insulin sensitivity." (PMID 39861488, 2025).
Insulin resistance (continued). "These metabolic alterations are thought to reflect either the effect of insulin or the degree of insulin resistance in these individuals." (PMID 40951687, 2025). "Insulin resistance develop due to secretion of placental hormones in pregnancy, antagonizes insulin." (PMID 40126146, 2025). "Resistin influences the synthesis of critical pro-inflammatory cytokines, including TNFα, IL6, and IL12, by activating NF-κB pathways in macrophages, leading to significant disruptions in peripheral insulin signaling and the development of insulin resistance." (PMID 40699839, 2025). "Insulin resistance and hyperlipidemia are frequently associated with MASH in mice and humans; therefore, we measured plasma levels of insulin, triglyceride (TG) and free fatty acids (FFA) four weeks after AAV8 injections." (PMID 41047119, 2025). "Insulin resistance in the liver and various peripheral tissues and insufficient insulin secretion by β-cells play a major role in the development of DM." (PMID 39136514, 2025). "HOMA-IR is used to predict fasting glucose and fasting insulin levels, making it effective for observing various aspects of insulin resistance and pancreatic β-cell function." (PMID 39815341, 2025). "Associations and potential interactions between CDAI and genotype on insulin and homeostatic model assessment for insulin resistance (HOMA-IR) were examined using multivariate regression and two-way ANOVA." (PMID 40732969, 2025). "Purple potato extract prevented the hypertrophy of islets as well as normalized glucose utilization and insulin level, suggesting the ameliorating effect in glucose intolerance and insulin resistance." (PMID 40168333, 2025). "The authors suggested these improvements were linked to healthier dietary habits, increased physical activity, and weight management, all contributing to reduced insulin resistance and improved insulin sensitivity." (PMID 40563120, 2025). "Concurrently, a high concentration of glucose, insulin, and serum lipids not only exacerbates the vascular damage but also accelerates the atherosclerosis progression and insulin resistance." (PMID 41227734, 2025). "Given that obesity is characterized by insulin resistance and insulin plays a crucial role in maintaining glucose homeostasis, we aimed to investigate the specific impact of hepatic Olfr734 knockdown on this parameter in DIO mice." (PMID 40806011, 2025). "Previously, we found that rats fed soft pellets (SPs) on a 3-h restricted schedule over 14 wk demonstrated glucose intolerance and insulin resistance with disruption of insulin signaling." (PMID 40074175, 2025). "Insulin resistance was assessed via oral glucose tolerance tests (OGTTs) and intraperitoneal insulin tolerance tests (IPITTs)." (PMID 41373625, 2025). "Recognized as a more precise way to measure insulin sensitivity, higher METS-IR values signal greater insulin resistance and a heightened risk of metabolic disorders." (PMID 41404507, 2025). "In the case of insulin resistance, the demand for insulin is greater, which requires islet beta cells to produce more insulin to meet the body’s needs." (PMID 40620676, 2025). "Insulin resistance, a common feature of obesity, can lead to increased levels of circulating insulin." (PMID 40034545, 2025). "Our previous research demonstrated that d-allulose improves insulin resistance in HF and high-sucrose obesity rat models using the insulin clamp method." (PMID 40573161, 2025). "Furthermore, magnesium deficiency also impairs insulin signaling, which may contribute to insulin resistance by disrupting certain key pathways, such as the insulin receptor substrate-1, its interaction with phosphatidyl-inositol 3 kinase, and reduced Akt phosphorylation." (PMID 41010443, 2025). "The homeostatic model assessment for insulin resistance (HOMA-IR) was calculated using fasted glucose and insulin concentrations at the end of treatment to give an approximation of insulin resistance." (PMID 40639664, 2025).
Insulin resistance (continued). "Insulin resistance prevents cells from efficiently responding to insulin, resulting in persistent hyperglycemia and an increased demand for insulin production, which, over time, exhausts β-cells." (PMID 40282289, 2025). "Type 2 diabetes (T2D) is a chronic metabolic disorder characterized by persistent hyperglycemia, primarily due to insulin resistance and the failure of beta cells to secrete sufficient insulin." (PMID 39859351, 2025). "This is one of the first studies showing this effect, highlighting the role of the liver in regulating glucose metabolism, insulin utilization, and insulin resistance." (PMID 40664615, 2025). "MG, in turn, can affect insulin signaling, further compromising the molecular basis of insulin resistance and creating a vicious cycle." (PMID 41295276, 2025). "Insulin resistance reduces the sensitivity of tissue cells to insulin, impairing glucose utilization and increasing the burden on β-cells." (PMID 40109716, 2025). "Unlike the distinction between “good” and “optimal,” which appears to be driven by insulin resistance, the primary factor separating “marginal” from “failed” function is the presence of residual insulin secretion." (PMID 40755872, 2025). "Based on 2 h insulin values, insulin resistance (defined as levels > 80 mU/mL) was identified in 44.5%." (PMID 40868057, 2025). "Concurrently, endothelial dysfunction impairs insulin-stimulated glucose disposal, contributing to insulin resistance." (PMID 40568618, 2025). "Multiple parallels between impaired brain insulin signaling in AD and insulin resistance in T2DM have been reported." (PMID 40778306, 2025). "Central insulin resistance further reinforces this connection by disrupting the brain’s insulin signaling, which is essential for synaptic plasticity, glucose metabolism, neuronal survival, and cognitive function." (PMID 40710317, 2025). "Studies on Psammomys obesus have shown that IL-1β-induced apoptosis of pancreatic islet cells reduces insulin production, potentially exaggerating the level of insulin resistance through subsequent hyperglycemia." (PMID 40564199, 2025). "Regarding insulin resistance, we directly assessed myotube response to insulin stimulation using pAkt expression following each treatment condition." (PMID 40422898, 2025). "MQC imbalance exacerbates insulin resistance, while impaired insulin signaling reciprocally compromises mitochondrial function, creating a vicious cycle of metabolic deterioration." (PMID 40866350, 2025). "Significant improvements were also observed in insulin resistance indicators, including fasting insulin levels, HOMA-IR index, QUICKI (p < 0.0001), and adiponectin (p = 0.04)." (PMID 40277805, 2025). "Daily consumption of the polyphenol quercetin, 1000 mg for 12 weeks, was shown to be effective in reducing insulin resistance, insulin levels, testosterone, and LH serum levels in PCOS women." (PMID 40362796, 2025). "Gestational diabetes mellitus (GDM) is a complex metabolic disorder, and it is characterized by inadequate insulin secretion and insulin resistance." (PMID 41293068, 2025). "Clinically, reductions in fasting insulin reflect enhanced peripheral glucose uptake and reduced insulin resistance, key protective factors against the progression of type 2 diabetes and metabolic syndrome." (PMID 40868925, 2025). "Treatment of T2DM focuses on improving insulin homeostasis and reducing peripheral insulin resistance." (PMID 39996055, 2025). "The probiotic also reduced serum insulin levels, the homeostasis model assessment of insulin resistance (HOMA-IR), and leptin levels, indicating improved metabolic regulation." (PMID 40218922, 2025). "High GI of food resulted in rapid absorption of carbohydrates that evoked high postprandial blood glucose levels and insulin concentrations which lead to the development of insulin resistance and the incidence of T2D." (PMID 40170678, 2025).